LPL (lipoprotein lipase)
Diseases named in the same sentence as LPL in open-access papers (continued):
Sharing a sentence is not in itself a finding about the gene and the disease.
dyslipidemia (continued). "In the case of PLH, it is unclear whether low LPL levels are also observed, as seen in metabolic syndrome." (PMID 41156460, 2025). "Elevated levels of IL-1, IL-6, and TNF-α in LPP may impair TG clearance by inhibiting lipoprotein lipase activity and reducing apoprotein-E levels, thus contributing to dyslipidemia." (PMID 40568287, 2025). "This study highlights the role of LPL as a contributing factor of dyslipidemia in PLH." (PMID 41156460, 2025). "Dyslipidemia in patients with proteinuria could be explained by altered lipid metabolism due to impaired lipoprotein lipase activity, decreased hepatic lipase activity and the presence of anti-lipoprotein lipase antibodies." (PMID 39696576, 2024). "Dyslipidemia is a physiological response in pregnancy driven by secretion of steroid hormone (e.g., progesterone), increased hepatic synthesis of triglycerides, and reduced lipoprotein lipase activity in adipose tissue." (PMID 39221169, 2024). "Dyslipidemia may also arise due to the reduced activity of liver lipoprotein lipase and hepatic triglyceride lipase enzymes, which are influenced by uremic toxins and high levels of apoprotein C-III." (PMID 39439522, 2024). "The EE mechanisms responsible for alleviating dyslipidemia and AI may relate to the increased lipoprotein lipase activity that mediates triglyceride hydrolysis and hepatic cholesterol excretion." (PMID 36979171, 2023). "Indeed, inflammation and its cytokine-mediated changes in lipase activity (e.g., incretins, lipoprotein lipase, and cholesteryl ester transfer protein activity) potentially drive the alteration of atherogenic dyslipidemia." (PMID 36691001, 2023). "Isoflavones may increase HDL-cholesterol production in the liver and ameliorate dyslipidemia by suppressing adipogenesis and activating lipoprotein lipase." (PMID 37305085, 2023). "One possibility is that Sparcl1 might regulate the PPARγ signal pathway and LPL expression, thereby regulating lipid metabolism and the development of dyslipidemia." (PMID 36387870, 2022). "A multivariable analysis was performed to assess whether the ANGPTL4, ApoC3, and LPL axis was altered in RA and to study its relationship with RA dyslipidemia and subclinical carotid atherosclerosis." (PMID 35488290, 2022). "Resistance training improves cardiometabolic profile via lipoprotein lipase activity enzyme stimulation and thus, it may protect against the onset of health conditions such as atherosclerosis, metabolic syndrome, and cardiovascular diseases." (PMID 36216952, 2022). "This alteration could reduce the transcriptional activity and regulate the lipoprotein lipase activity, thereby affecting the removal of triglycerides, which leads to atherosclerosis due to dyslipidemia." (PMID 34758198, 2021). "In this study, we reported two neonatal LPL cases with yellowish skin and dyslipidemia." (PMID 34544385, 2021). "Moreover, future studies using an LPL agonist alone or in combination with a CETP inhibitor need to be conducted in order to investigate the possibility of LPL as a therapeutic target of dyslipidemia and CVD." (PMID 31234537, 2019). "However, Odds (dyslipidemia| GG) was 1.5 in LPL HindIII [rs320] showing that this was possibly a good feature for the proposed classifier." (PMID 30026888, 2018). "Moreover, IH-induced dyslipidemia can also be related to decreased lipoprotein clearance due to the inhibition of lipoprotein lipase (LPL) mediated by HIF-1 and Angiopoietin-Like 4 (Angptl4)." (PMID 25834642, 2015). "It was suggested in the CHIBA study that pitavastatin may facilitate remnant lipoprotein catabolism by upregulating LPL activity in Japanese patients with metabolic syndrome." (PMID 24098467, 2013). "The lack of anti-LPL antibodies in Takayasu's disease implies distinct mechanisms underlying dyslipidemia compared to systemic lupus erythematosus." (PMID 19606253, 2009).
dyslipidemia (continued). "Therefore, it is recommended to evaluate for a pathogenic variant in the LPL gene in children with T1DM who do not have dyslipidemia but exhibit the rare triad of AP, HTG, and DKA." (PMID 40747209, 2025). "Additionally, everolimus may lower levels of lipoprotein lipase activity and increase free fatty acid levels, which can contribute to dyslipidemia." (PMID 37692846, 2023). "Its dysfunction may impact LPL activity and availability, and this then results in dyslipidemia." (PMID 37768328, 2023). "In addition, the N-acetylgalactosamine transferase 2-angiopoietin like protein 3-lipoprotein lipase (GALNT2-ANGPTL3-LPL) pathway, which is closely related to dyslipidemia and able to directly affect HDL metabolism, has been reported to be effectively regulated by paeoniflorin." (PMID 37324475, 2023). "Additionally, rs117026536 in the LPL gene, rs651821 in the APOA5 gene, rs9926440 in the CETP gene, and rs429358 in the APOE gene were associated with dyslipidemia.The GWAS analysis of the male subjects revealed 13 significant SNPs in the discovery stage (P < 5 × 10− 8)." (PMID 36419087, 2022). "Moreover, Propolis improves the lipoprotein lipase activity in the vessels (similar to lipid-lowering medications, such as fibrates) while inhibiting the hormone-sensitive lipase activity in adipose tissue, all leading to improved dyslipidemia." (PMID 35057819, 2022). "In addition, it has been reported that LPL concentration is inversely correlated with intra-abdominal visceral fat accumulation, as evaluated by computed tomography, and with the number of metabolic syndrome symptoms." (PMID 30947712, 2019). "Also inflammatory factors decrease lipoprotein lipase activity in autoimmune skin diseases such as lichen planus, psoriasis, or pemphigus vulgaris which may result in dyslipidemia so we excluded these patients from this research." (PMID 29861719, 2018). "Another example of the use of ASOs in the context of metabolic syndrome involves targeting ANGPTL8, which regulates the expression of lipoprotein lipase (LPL)." (PMID 39944202, 2025). "The angiopoietin-like protein 3/8 complex (ANGPTL3/8) inhibits lipoprotein lipase (LPL) activity, primarily in oxidative tissues, and does so more potently than ANGPTL3, making ANPTL3/8 an attractive target for treating dyslipidemia." (PMID 40640392, 2025). "In the present study, chronic HFD feeding suppressed PPARα activation in the liver, which, in turn, downregulated lipolysis and fatty acid oxidation-related gene levels (LPL, CPT-1a, and ACOX1) and ultimately led to hepatic lipid deposition and dyslipidemia." (PMID 39942052, 2025). "Lipoprotein lipase (LPL) mediates the formation of LDL, a major element of dyslipidemia, in muscle tissue and adipose tissue." (PMID 37510094, 2023). "These lead to changes in key metabolic pathways, including inhibition of lipoprotein lipase, peroxisome proliferator-activated receptor-gamma (PPARꝩ) and glucose transporter (GLUT4), resulting in dyslipidemia, weight changes and dysglycemia." (PMID 37507703, 2023). "ANGPTL3 has been reported to play a critical role in the inhibition of LPL activity to regulate atherogenic TGRL metabolism in plasma and dyslipidemia." (PMID 36293338, 2022). "ANGPTL3 has been reported to be mainly involved in the suppression of LPL activity to affect atherogenic TGRL metabolism and dyslipidemia." (PMID 34576019, 2021). "This strong link is unsurprising, as in metabolic syndrome, the liver production of very low density lipoprotein (VLDL) is increased and subsequent hydrolysis of VLDL by lipoprotein lipase increases circulating FFA." (PMID 33291273, 2020).
dyslipidemia (continued). "In adipocytes, TNFα reduces the secretion of adiponectin, induces IR and favors atherogenic dyslipidemia due to the reduction in GLUT4 expression, reduction in lipoprotein lipase (LPL) activity and increasing in expression of hormone-sensitive lipase." (PMID 26578976, 2015). "Corticosteroids are thought to induce dyslipidemia through impaired catabolism of LDL, and increased lipoprotein lipase activity." (PMID 19684849, 2009). "Corticosteroids are thought to induce dyslipidemia through increased production of HDL, impaired catabolism of LDL, and increased lipoprotein lipase activity." (PMID 20157365, 2008). "Classically, dyslipidemia in CKD is characterized by elevated triglyceride and low HDL cholesterol levels owing to decreased renal clearance and decreased activity of enzymes like lipoprotein lipase." (PMID 39940317, 2025). "This is the first study to report a negative correlation between the expression of the FTO gene and FBG, as well as the expression of the LPL gene, and a positive correlation between the expression of the FTO gene and cardiac troponin 1 in AF subjects with metabolic syndrome." (PMID 39166676, 2024). "The mechanisms behind glucocorticoid-induced dyslipidemia may include impaired LDL catabolism, increased lipoprotein lipase activity, and subsequent elevation of LDL level due to increased plasma insulin." (PMID 39759349, 2024). "Dyslipidemia is a common finding in human patients with IBD and it can be attributed to the elevation of inflammatory cytokines such as TNF-α, interferon C, and interleukin-1 that inhibit lipoprotein lipase activity." (PMID 39195803, 2024). "This study compared the clinical characteristics and rare variants in the LPL gene of patients with HLAP and patients with BAP who have or do not have dyslipidemia." (PMID 38530959, 2024). "Many genes such as APOB, LPL, APOA1, LEP, CD36, IL-6, and APOE may play an important role in dyslipidemia." (PMID 36061816, 2022). "In addition, the administration of PPAR-α agonists was related to the decrease of the LPL inhibitor apolipoprotein C III in patients affected by metabolic syndrome, type 2 diabetes and dyslipidemia." (PMID 33348908, 2020). "SLKDT extracts upregulated mRNA expressions of PPAR‐α, LPL, CPT1, and CYP7A1 and downregulated mRNA expressions of PPAR‐γ and C/EBP‐α, which reduced adipocyte differentiation and fat accumulation, promoted fat oxidation, and improved dyslipidemia." (PMID 32884731, 2020). "Fibrates are used especially in hypertriglyceridemia and mixed dyslipidemia, acting as agonists on peroxisome proliferator-activated receptor-alpha (PPAR-alpha) which leads to the activation of lipoprotein lipase with the subsequent degradation of VLDL fraction rich in triglycerides." (PMID 32695007, 2020). "SLKDT downregulated PPAR‐γ and C/EBP‐α mRNA expressions and upregulated PPAR‐α, CPT‐1, LPL, and CYP7A1 mRNA expressions to reduce adipocyte differentiation and fat accumulation, accelerate fat oxidation, and improve dyslipidemia, then inhibit the immune response and alleviate liver injury." (PMID 32884731, 2020). "Pathway No. 12 (Visceral fat deposits and the metabolic syndrome) is a pathway related to the glucocorticoid receptor, which will activate/inactivate the lipoprotein lipase, TNF-alpha, and insulin resistance." (PMID 29379041, 2018). "The different effects of AngII on LPL expression and, hence, TG metabolism in VAT and SAT may partly explain their different contributions to the development of metabolic syndrome." (PMID 26447765, 2015). "In spite of the high frequency of dyslipidemia and inflammatory markers in these patients no anti-LPL were detected." (PMID 19606253, 2009). "Genetic variations in lipid metabolism genes, such as LPL or APOE, which play a role in lipid homeostasis and vascular function, can be altered by environmental factors such as diet or physical activity, thereby influencing the onset of dyslipidemia and its subsequent vascular consequences." (PMID 41234028, 2025).
dyslipidemia (continued). "Additionally, lipoprotein lipase (LPL) activity at injury sites may contribute to localised TG hydrolysis, enhancing hepatic VLDL synthesis and perpetuating dyslipidemia." (PMID 40638555, 2025). "Mechanisms such as tumor necrosis factor-alpha (TNF-α)-mediated inhibition of lipoprotein lipase, low lipoprotein activity, and the presence of antibodies to lipoprotein lipase found in patients with SLE have been suggested to contribute to the pathophysiology of dyslipidemia in SLE." (PMID 39981087, 2025). "The lack of inhibitory activity on LpL and stimulatory activity on hepatic VLDL secretion, confirmed once again in the present study, are key to this variant’s favorable lipid profile, positioning it as a promising therapeutic tool for metabolic syndrome." (PMID 41354325, 2025). "Also, it has been investigated that zinc cooperates in lipoprotein lipase and lecithin cholesteryl ester transferase pathways; thus, it is proposed that ZNF202 may be a probable gene vulnerable to developing dyslipidemia in human body." (PMID 37604307, 2023). "Previous studies have shown that CIH can induce dyslipidemia and atherosclerosis in ApoE−/− mice by inhibiting the expression and activity of LPL and affecting the expression of Angptl4, a potential inhibitor of LPL in adipose tissue but not in heart tissue." (PMID 36285165, 2022). "Unlike the contradictory data from the LPL activator, abrogating the inhibitory effects of ApoC3 and ANGPTLs on LPL activity consistently reduces circulating TG levels, thus yielding promising outcomes of dyslipidemia in different experimental animal models." (PMID 35187136, 2022). "The heparan sulphate side chains of collagen XVIII are suggested to carry LPL from the ECM to its receptor on the endothelial cell membrane, and a lack of this collagen may lead to the retention of LPL in the subendothelial matrix, leading to dysregulation in blood lipid profiles and dyslipidemias." (PMID 37239083, 2023). "The attenuation of dyslipidemia by curcumin supplementation could in turn improve the glucose metabolic status of T2DM patients, and multiple molecular targets including PPAR-γ, cholesteryl ester transfer protein, and lipoprotein lipase who contribute to the beneficial effects of curcumin." (PMID 35754684, 2022). "Although some of these studies have focused on genomic regions that are confirmed to harbor dyslipidemia-predisposing loci, such as APOB, CETP, LIPC and LPL, no exhaustive studies testing whether GWAS-discovered loci modify response to treatments have been previously reported." (PMID 22951888, 2012).
atherosclerosis (142 papers, 2002 to 2025). A disease characterized by the build-up of fatty material and calcium deposition in the arterial wall resulting in partial or complete occlusion of the arterial lumen. "On the other hand, LPL overexpression is associated with increased LPL activity, decreased plasma triglycerides, and reduced atherosclerosis." (PMID 39590382, 2024). "Both Angptl4-ab and DLT treatment reversed the changes in lipid concentration, LPL activity, and atherosclerosis caused by CIH." (PMID 36285165, 2022). "Intriguingly, among these secreted proteins, PLTP, CD5L, and LPL have been reported to exacerbate or be associated with advanced atherosclerosis, whereas IL18BP is anti‐atherogenic." (PMID 33231376, 2021). "One would predict that LMF1 loss-of-function mutations would have effects on atherosclerosis surpassing those of LPL-deficiency because LMF1 is also needed for maturation of HL and EL." (PMID 32849290, 2020). "Recently, mice with inducible LPL-deficiency have been used to study regression of lesions of atherosclerosis." (PMID 32849290, 2020). "Conversely, ANGPTL4-deficient mice exhibit increased plasma LPL activity, increased TG clearance, decreased plasma TG levels, and reduced atherosclerosis." (PMID 32849290, 2020). "It has been reported that CETP increases small-size HDLs and small LDLs by interacting with LPL, increasing the risk of atherosclerosis." (PMID 31234537, 2019). "We are currently investigating a rodent study by using apolipoprotein E-knockout (apoE KO) mice as our mice model to induce atherosclerosis and identify the role of the LPL inhibitor NDGA on CVD risk and HDL subpopulations." (PMID 31234537, 2019). "Any deficiency in LPL activity leads to lipid metabolism defects such as hyperlipidemia and atherosclerosis, which are the main risk factors for myocardial infarction and stroke." (PMID 30140409, 2018). "We demonstrate that adipose ANGPTL4 governs plasma TAG levels by modulating LPL activity, and as a consequence, impacts associated metabolic outcomes including progression of atherosclerosis and glucose homeostasis in mice." (PMID 29563332, 2018). "Several polymorphic variants of the LPL gene have been identified in recent years and evaluated for their effects on plasma lipids and atherosclerosis risk from different populations." (PMID 22837712, 2012). "The lipoprotein lipase (LPL) gene represents an excellent candidate to explain parts of the genetically determined risk of atherosclerosis." (PMID 22837712, 2012). "With this specific hypertriglyceridemic (HTG) model, we have determined the effects of LPL deficiency on atherosclerosis development, pancreatitis susceptibility and cognitive function." (PMID 21980507, 2011). "In a previous study,we reported the occurrence of spontaneous atherosclerosis in LPL deficient HTG mice older than 15 months,which was further confirmed by a recent report on atherogenicity in Gpihbp1-deficient HTG mice." (PMID 21980507, 2011). "Anti-LPL autoantibodies have been implicated in the inflammatory mechanisms of atherosclerosis in SLE and other inflammatory autoimmune disease with an evident vascular damage." (PMID 19606253, 2009). "Recently Taylor and associates reported on the influence of lipoprotein lipase locus on the progression of atherosclerosis in coronary artery bypass grafts and identified the LPL-HINDIII 2/2 genotype as an independent risk factor." (PMID 19691831, 2009). "Previous studies have shown that increased LPL activity is associated with improved lipid profiles, particularly the reduction of triglycerides in circulation, which in turn can reduce the risk of atherosclerosis and other CVDs." (PMID 40223248, 2025). "Thus, macrophage LpL deficiency in the iLpl−/−/Ldlrkd model should have reduced atherosclerosis, making the increase in lesion size even more impressive." (PMID 39649171, 2024).